FARSB (phenylalanyl-tRNA synthetase subunit beta)
Synonyms: PheRS; FARSLB; FRSB; HSPC173; PheHB; NEDBLLA; RILDBC; RILDBC1; RJBS
Tractability: Small molecule: a structure with a bound ligand is known; a high-quality ligand is known. PROTAC: ubiquitination databases record sites on it; its protein half-life has been measured; a small molecule that binds it is known.
Target class: Enzyme; Ligase
Gene: Protein-coding gene on chromosome 2 (222,566,899 to 222,656,313, reverse strand). Ensembl gene ENSG00000116120.
Subcellular location: Cytoplasm
Subcellular location (Human Protein Atlas): Nucleoplasm; Cytosol
Pathways (Reactome):
Metabolism of proteins: Cytosolic tRNA aminoacylation
Gene Ontology:
Molecular function: phenylalanine-tRNA ligase activity; protein binding; magnesium ion binding; ATP binding; nucleotide binding; RNA binding
Biological process: phenylalanyl-tRNA aminoacylation; protein heterotetramerization; translation
Cellular component: cytosol; membrane; nucleoplasm; phenylalanine-tRNA ligase complex; cytoplasm
Genetic constraint (gnomAD): Loss-of-function variants: 9 observed, 13.89 expected, observed/expected ratio (o/e) 0.65, 90% interval 0.39 to 1.13. The upper end of that interval is the gene's LOEUF score, 1.13, which puts it in group 4 of 6, group 1 being the genes least tolerant of losing a copy. Missense variants: 197 observed, 209.6 expected, observed/expected ratio (o/e) 0.94, 90% interval 0.84 to 1.06. Synonymous variants: 84 observed, 79.77 expected, observed/expected ratio (o/e) 1.05, 90% interval 0.88 to 1.26.
Homologues: Orthologues: chimpanzee FARSB (99% identical), macaque FARSB (99% identical), rabbit FARSB (95% identical), guinea pig FARSB (94% identical), mouse Farsb (94% identical), rat Farsb (93% identical), tropical clawed frog farsb (79% identical), zebrafish farsb (76% identical), Drosophila melanogaster beta-PheRS (62% identical), Caenorhabditis elegans fars-3 (60% identical). Paralogues in human: LRRC47 (16% identical).
Diseases named in the same sentence as FARSB in open-access papers:
FARSB is named in the same sentence as 28 diseases in open-access papers, as found by Europe PMC text mining. Sharing a sentence is not in itself a finding about the gene and the disease. The quoted sentences say what the papers report.
interstitial lung disease (5 papers, 2018 to 2023). A diverse group of lung diseases that affect the lung parenchyma. "Autosomal recessive inheritance of pathogenic variants of FARSA or FARSB can result in defective FARS1 which are characterized by interstitial lung disease, liver disease, brain abnormalities, facial dysmorphism and growth restriction." (PMID 37833669, 2023). "FARSB (Phenylalanyl-TRNA Synthetase Subunit Beta) is an aminoacyl tRNA synthase (ARSs), it has been shown to be associated with brain calcification, interstitial lung disease and liver cirrhosis." (PMID 37074800, 2023). "Mutations in the FARSB gene have been associated with aminoacyl-tRNA synthetase-related diseases including cerebral aneurysms, brain calcifications, cirrhosis, and interstitial lung disease." (PMID 34945756, 2021). "Mutation of the FARSB gene leads to a multisystem disease, aminoacyl-tRNA synthetase-related diseases, characterised by the following clinical features: brain calcifications, cerebral aneurysms, interstitial lung disease, and cirrhosis." (PMID 33947873, 2021).
liver cancer (3 papers, 2022 to 2023). An epithelial or non-epithelial malignant neoplasm that arises from the liver. "We found that the high expression of FARSB in liver cancer is closely related to patients’ low survival and poor prognosis." (PMID 38069034, 2023). "FARSB protein levels were significantly up-regulated in liver cancer tissues compared to adjacent tissues." (PMID 38069034, 2023). "In liver cancer cells, the mRNA and protein expression levels of FARSB are increased and promote cell proliferation and migration." (PMID 38069034, 2023). "In our study, the possible participation mechanism of FARSB in liver cancer was analyzed using bioinformatics methods based on data from multiple online open databases." (PMID 37074800, 2023). "The results showed that FARSB may be an independent prognostic factor for patients with liver cancer." (PMID 38069034, 2023). "In summary, FARSB inhibits ferroptosis in liver cancer cells by activating mTORC1 expression, which may be an essential mechanism for FARSB to promote HCC progression." (PMID 38069034, 2023). "Therefore, to further investigate the possible mechanism of FARSB overexpression in liver cancer, we studied the methylation of FARSB promoter in liver cancer, and observed that in HCC patients, the degree of promoter methylation was negatively correlated with FARSB expression." (PMID 37074800, 2023). "The high expression of FARSB may constitute an immunosuppressive microenvironment by affecting the expression levels of relevant chemokines, CCL26 and CX3CL1, and helping the infiltration of Th2 cells, resulting in a poor prognosis for liver cancer patients." (PMID 37074800, 2023). "Therefore, the high expression of FARSB may constitute an immunosuppressive microenvironment by affecting the expression levels of relevant chemokines, CCL26 and CX3CL1, and helping the infiltration of Th2 cells, resulting in a poor prognosis for liver cancer patients." (PMID 37074800, 2023).
hepatocellular carcinoma (2 papers, 2023). A malignant tumor that arises from hepatocytes. "Subsequently, the immunofluorescence intensity of FARSB in two hepatocellular carcinoma cell lines (Huh7 and MHCC97H) was significantly higher than that of LO2." (PMID 38069034, 2023). "Compared with adjacent tissues, the expression level of FARSB in hepatocellular carcinoma tissues was significantly up-regulated." (PMID 38069034, 2023). "In our research, we first identified elevated mRNA levels of FARSB in hepatocellular carcinoma compared to normal tissues through the Timer online website." (PMID 37074800, 2023). "Then, we investigated the link between FARSB expression and the infiltrating immune cells (hepatocellular carcinoma) by utilized TIMER “Gene” module." (PMID 37074800, 2023). "After discovering the close relationship between expression and clinicopathological features, we then went on to discover the prognostic value of FARSB expression in hepatocellular carcinoma." (PMID 37074800, 2023). "Our research exposed that FARSB was highly expressed in hepatocellular carcinoma." (PMID 37074800, 2023). "We then further explored the prognostic value of FARSB expression in hepatocellular carcinoma using single multifactor Cox analysis, and the results showed that FARSB could be considered as an independent predictor." (PMID 37074800, 2023). "In conclusion, our results suggest that FARSB is a novel hepatocellular carcinoma biomarker and may be used as a prognostic factor for human HCC." (PMID 37074800, 2023). "Nevertheless, the research about FARSB biological function and mechanism in hepatocellular carcinoma has not been put forward, and FARSB correlation with prognosis is unclear." (PMID 37074800, 2023). "However, the mechanism by which FARSB affects the progression of hepatocellular carcinoma is not yet precise." (PMID 38069034, 2023).
Lung Disease (2 papers, 2020 to 2022). "A study on bi-allelic mutations in FARSB revealed that patients could present a multi-organ pulmonary disease without defects in protein synthesis when measured by puromycin incorporation in the disease-affected patient tissues." (PMID 33266490, 2020).
colorectal cancer (1 paper, 2023). A primary or metastatic malignant neoplasm that affects the colon or rectum. "Studies have shown that FARSB is associated with tumors, and FARSB may be a downstream gene of the critical tumor suppressor gene IGFBP7 in colorectal cancer." (PMID 38069034, 2023).
gastric cancer (1 paper, 2022). A primary or metastatic malignant neoplasm involving the stomach. "Previous studies have shown that FARSB is involved in amino acid metabolism and tRNA aminoacylation, and plays a key role in the progression of gastric cancer." (PMID 35836576, 2022).
gastric tumor (1 paper, 2023). "Furthermore, previous reports have indicated that FARSB is overexpressed in gastric tumor tissues and is associated with a poor prognosis and tumorigenesis." (PMID 37074800, 2023).
mental disorder (1 paper, 2021). A disease that has its basis in the disruption of mental process. "However, since no previous studies have reported how FARSB proteins are expressed in mental disorders, the underlying pathogenesis of FARSB with BD-II requires further study." (PMID 33947873, 2021).
Obesity (1 paper, 2024). Accumulation of substantial excess body fat. "Because fragmentation of human FARS has also been observed in human cells and mutations in human β-PheRS (FARSB) can lead to problems in gaining weight, Drosophila β-PheRS can also serve as a model for the human phenotype and possibly also for obesity." (PMID 38374657, 2024).
peripheral nerve injury (1 paper, 2021). Injury to a peripheral nerve. "FARSB expression was found to be increased in dorsal horn neurons after peripheral nerve injury; FARSB has therefore been proposed as a neurotransmitter that may relay unusual sensory signals after peripheral nerve damage." (PMID 34945756, 2021).
testicular germ cell tumor (1 paper, 2025). A germ cell tumor arising from the testis. "This region, commonly altered in several cancer types (especially testicular germ cell tumors), contains four NMD-related genes (CWC22, SF3B1, NOP58, and FARSB)." (PMID 41023738, 2025).
cancer (6 papers, 2014 to 2025). A tumor composed of atypical neoplastic, often pleomorphic cells that invade other tissues. "In conclusion, the signaling pathways associated with high expression of FARSB can promote the progression of cancer." (PMID 37074800, 2023). "FARSB activates the mTORC1 signaling pathway by binding to the component Raptor of the mTORC1 complex and plays a role in promoting cancer." (PMID 38069034, 2023). "Mechanistically, FARSB activates the mTOR complex 1 (mTORC1) signaling pathway by binding to the component Raptor of the mTORC1 complex to play a role in promoting cancer." (PMID 38069034, 2023). "More interestingly, FARS2 is down-regulated in KICH, while the two paralog ARSs, FARSA and FARSB, are up-regulated in six and four cancer types, respectively." (PMID 30588513, 2018). "While three of the chimeras (ACTB->POTEM, ACTB->POTEE and SP100->HMGB1) have been found in normal population, three of the chimeras (C2orf27A->NBEA, HILPDA->EFCAB3, FARSB->TRIM61) were previously identified only in cancer samples." (PMID 25133550, 2014). "In order to verify the cancer-promoting effect of FARSB in HCC, the FARSB knockdown cell model was constructed by transfecting Huh7 and MHCC97H with siFARSB." (PMID 38069034, 2023). "As shown in our results, these genes, especially FARSB, could activate Cell Cycle, DNA Damage Response, Hormone AR pathways, TSC/mTOR and inhibit EMT, Hormone ER, PI3K/AKT, RAS/MAPK, RTK pathways to play a regulatory role in the cancer process." (PMID 37074800, 2023).
neurodevelopmental disorder (3 papers, 2020 to 2023). A behavioral and cognitive disorder with onset during the developmental period that involves impaired or aberrant development of intellectual, motor, or social functions. "FARSB is implicated in human phenylalanine synthesis, and mutations in the FARSB gene have been associated with neurodevelopmental disorders affecting the brain, liver, and lungs." (PMID 37988184, 2023). "Pathogenic mutations in the FARSB gene are associated with neurodevelopmental disorder involving the brain, liver, and lungs." (PMID 35937029, 2022).
tumor (3 papers, 2019 to 2023). "And TIMER analysis revealed that the FARSB expression was closely linked to tumor purity and immune cell infiltration." (PMID 37074800, 2023). "The high expression of FARSB was associated with tumor grade and T stage." (PMID 38069034, 2023). "This suggests a new direction for tumor immunotherapy in patients with high expression of FARSB, and is closely related to m6A modification and drug sensitivity." (PMID 37074800, 2023). "On the contrary, MHCC97H cells with FARSB overexpression had a faster tumor growth rate than the control group, and rapamycin can block the effect of FARSB on promoting tumor progression." (PMID 38069034, 2023). "To explore in depth the role of FARSB in tumor immunity, we investigated the correlation between FARSB and immune cell biomarkers in HCC." (PMID 37074800, 2023). "And up-regulation of FARSB expression promoted tumor immune cell infiltration and checkpoint expression." (PMID 37074800, 2023). "According to this graph FARSB expression was positively related to the tumor purity and infiltration of some immune cells (P< 0.05)." (PMID 37074800, 2023). "The result showed that high FARSB expression was obviously related to age, grade, stage and tumor size." (PMID 37074800, 2023). "Subsequently, immunohistochemical analysis of the tumor was performed to detect FARSB and proliferating cell nuclear antigen (PCNA)." (PMID 38069034, 2023). "Therefore, we used the GeneMANIA database to establish an interaction network between FARSB and other tumor-related proteins." (PMID 37074800, 2023). "We further studied the role of FARSB in vivo through a xenograft tumor model." (PMID 38069034, 2023). "Rapamycin can block the tumor-promoting effect of FARSB overexpression in HCC, proving that FARSB activates the mTORC1 signaling pathway to promote the proliferation and migration of HCC cells." (PMID 38069034, 2023).
FARSB also shares sentences with these, for which no sentence is quoted: calcification (2 papers); cerebral aneurysms (2); liver cirrhosis (2); bipolar II disorder (1); Cerebral calcification (1); Cirrhosis (1); genetic disorder (1); Hypertension (1); intracranial aneurysms (1); liver disease (1); melanoma (1); muscular dystrophy (1); renal disease (1); schizophrenia (1).